GPR107 (G protein-coupled receptor 107)
Description:
Has been proposed to act as a receptor for neuronostatin, a peptide derived from the somatostatin/SST precursor. Involved in blood sugar regulation through the induction of glucagon in response to low glucose (By similarity). (Microbial infection) Required for intoxication by Pseudomonas aeruginosa exotoxin A and Campylobacter jejuni CDT. May contribute to the retrograde transport of bacterial toxins, including cholera toxin, from the trans-Golgi network to the endoplasmic reticulum.
Synonyms: KIAA1624; LUSTR1; RP11-88G17; FLJ20998; GCDRP; bA138E2.2
Tractability: Antibody: UniProt places it where antibodies can reach, with medium confidence; UniProt predicts a signal peptide or a membrane-spanning region; its Gene Ontology location is reachable by antibodies, with medium confidence. PROTAC: ubiquitination databases record sites on it; its protein half-life has been measured.
Gene: Protein-coding gene on chromosome 9 (130,053,426 to 130,140,169, forward strand). Ensembl gene ENSG00000148358.
Subcellular location: Cell membrane; Golgi apparatus, trans-Golgi network membrane
Subcellular location (Human Protein Atlas): Golgi apparatus; Nucleoplasm
Gene Ontology:
Molecular function: clathrin heavy chain binding
Biological process: clathrin-dependent endocytosis
Cellular component: clathrin-coated vesicle; membrane; plasma membrane; early endosome; Golgi apparatus
Genetic constraint (gnomAD): Loss-of-function variants: 5 observed, 13.58 expected, observed/expected ratio (o/e) 0.37, 90% interval 0.19 to 0.77. The synonymous counts are far from expectation, so gnomAD's model fits this gene poorly and the ratio says little. Missense variants: 153 observed, 159.16 expected, observed/expected ratio (o/e) 0.96, 90% interval 0.84 to 1.1. Synonymous variants: 92 observed, 68.39 expected, observed/expected ratio (o/e) 1.35, 90% interval 1.14 to 1.6.
Homologues: Orthologues: chimpanzee GPR107 (99% identical), macaque GPR107 (98% identical), dog GPR107 (92% identical), pig GPR107 (91% identical), rabbit GPR107 (86% identical), mouse Gpr107 (84% identical), guinea pig GPR107 (83% identical), rat Gpr107 (78% identical), tropical clawed frog gpr107 (62% identical), zebrafish gpr107 (58% identical), Drosophila melanogaster CG12121 (46% identical), Caenorhabditis elegans C15H9.5 (31% identical), and 2 more. Paralogues in human: GPR108 (48% identical), TMEM87A (17% identical), TMEM87B (17% identical).
Diseases named in the same sentence as GPR107 in open-access papers:
GPR107 is named in the same sentence as 9 diseases in open-access papers, as found by Europe PMC text mining. Sharing a sentence is not in itself a finding about the gene and the disease. The quoted sentences say what the papers report.
breast carcinoma (1 paper, 2019). "Hypomethylation of this SE is strongly linked to overexpression of GPR107 (G Protein-Coupled Receptor 107), which is commonly overexpressed in breast cancer patients with worth prognosis." (PMID 31636280, 2019).
hyperlipidemia (1 paper, 2025). "Even though the PHS computed for hyperlipidemia to embolectomy was not significant, this PHS included interesting SNPs such as the GPR107 (3 prime UTR variant rs1306, beta −0.058) that had a protective effect for the disease progression." (PMID 39974115, 2025).
kidney damage (1 paper, 2025). "The GPR107-deficient mice with DN exhibit aggravated nephropathy, which characterized by the presence of a thickened GBM mainly resulting from an accumulation of COL4." (PMID 39932642, 2025). "The expression level of GPR107 in clinical kidney specimens was negatively correlated with the degree of kidney damage." (PMID 39932642, 2025). "Even though our data provide strong evidence for a crucial role of GPR107 in podocytes, we cannot exclude the possibility that other cells in the kidney (e.g., epithelial cells, endothelial cells, and glomerular mesangial cells) may contribute to kidney damage." (PMID 39932642, 2025).
cancer (2 papers, 2020 to 2024). A tumor composed of atypical neoplastic, often pleomorphic cells that invade other tissues. "When performing pairwise comparisons among the different stages of cancer, stage IV patients had increased expression of FGA, FGB, PERP, GPR107, CDH3 compared to controls." (PMID 39146279, 2024).
tumor (1 paper, 2020). "The first approach was to assess the effect of GPR107-silencing on cell proliferation and migration, two parameters tightly linked to tumor growth and metastasis, some of the main clinical problems associated to PCa." (PMID 32498336, 2020). "This revealed that GPR107 is present in a high proportion of PCa samples and is overexpressed, at both mRNA and protein levels, in PCa tissues, as compared to non-tumor tissues in two independent cohorts of human samples." (PMID 32498336, 2020). "GPR107 IHC analysis was performed on 16 FFPE pieces, which revealed that GPR107 staining was negligible in benign prostate gland epithelium (N-TAR), while it was always more, and highly, intense in the cancerous prostate glands (N-TAR vs. PCa/tumor-tissue)." (PMID 32498336, 2020). "In fact, this result indicating that silencing of GPR107 may inhibit cell proliferation/migration via negative regulation of AKT pathway is a common mechanism that has been previously reported with other components of the somatostatin system in different tumor types, including PCa." (PMID 32498336, 2020). "Analysis of GPR107 mRNA expression in FFPE-prostate pieces from patients diagnosed with localized PCa (n = 84; Gleason score 6–8) revealed that GPR107 expression was significantly higher in tumor vs. non-tumor adjacent regions (N-TAR)." (PMID 32498336, 2020).
GPR107 also shares sentences with these, for which no sentence is quoted: atherosclerosis (1 paper); cervical cancer (1); diabetic nephropathy (1); prostate tumors (1).